RXRB (retinoid X receptor beta)
Diseases named in the same sentence as RXRB in open-access papers (continued):
Sharing a sentence is not in itself a finding about the gene and the disease.
metastatic disease (1 paper, 2024).
oligoasthenoteratozoospermia (1 paper, 2022). A form of male infertility that is characterized by a combination of low number or oligozoospermia, poor motility or asthenozoospermia, and abnormal shape or teratozoospermia of sperms. "Also, mutation of the gene RXRB results in male sterility, due to oligoasthenoteratozoospermia." (PMID 35286314, 2022).
oral cancer (1 paper, 2014). "This study is the first to associate an RXRB-causal network with increased risks of nodal metastasis, tumor relapse, distant metastases and poor survival for oral cancer." (PMID 24322297, 2014).
steatosis (1 paper, 2022). Increased lipid within the cytoplasm of cells. "RXRB siRNAs were applied and verify its role in LINC01260 regulated OA-induced hepatocytes steatosis." (PMID 35016686, 2022).
thyroid carcinoma (1 paper, 2018). "To date, a high level of cytoplasmic expression of RXRB has been demonstrated in thyroid carcinoma; however, the expression of RAB39A has not been explored." (PMID 29515775, 2018).
triple-negative breast carcinoma (1 paper, 2018). An invasive breast carcinoma which is negative for expression of estrogen receptor (ER), progesterone receptor (PR), and human epidermal growth factor receptor 2 (HER2). "RXRB is also expressed in various malignancies and promotes cell survival/proliferation in triple-negative breast cancer, thus indirectly confirming a crucial role of the RAB39A-RXRB axis in modulating cancer stemness." (PMID 29515775, 2018).
Wegener's granulomatosis (1 paper, 2009). "A major genomic region involved in Wegener's granulomatosis includes the gene for retinoid receptor beta (RXRB) which forms heterodimers with peroxisome proliferator-activated receptors (PPARs)." (PMID 19223982, 2009).
cancer (22 papers, 1999 to 2026). A tumor composed of atypical neoplastic, often pleomorphic cells that invade other tissues. "To examine this in our cancer models, we compared the expression of RARα, RARβ, RARγ, RXRα, RXRβ and RXRγ in AB1-HA tumors, which are sensitive to combination tretinoin–CY therapy, and AE17, CT26 and WEHI164 tumors, which are resistant." (PMID 38350880, 2024). "Another study reported that the RXRB acted as a downstream effector of RAB39A to foster cancer cell stemness, and interfered with the histone deacetylase (HDAC) to maintain embryonic neuronal stem cells." (PMID 39465162, 2024). "RAB39A and RXRB thus deserve further investigation that will allow the development of novel drugs for more effective and novel anti-cancer therapeutic strategies." (PMID 29515775, 2018). "To confirm that RXRB is a downstream effector of RAB39A that fosters cancer stemness, we induced overexpression of RXRB in RAB39A-knockdown 143B cells and evaluated their sphere-formation ability and tumorigenesis in vivo." (PMID 29515775, 2018). "To further validate RAB39A and RXRB as potential targets for cancer therapy, we analyzed their expression levels in various malignancies from clinical samples." (PMID 29515775, 2018). "RXRB was also induced by hypoxia in 5 out of 6 cancer cells, especially in HeLa and 143B cells, even though it was reduced in MSC." (PMID 29515775, 2018). "In combination with a cellular functional analysis following RAB39A knockdown and RXRB augmentation, this strategy enabled us to identify RXRB as a downstream effector of RAB39A that fosters cancer stemness." (PMID 29515775, 2018). "As for RXRβ, although its expression was found stable in normal lung cells and cancer lines, a concomitant down-regulation was observed with RARβ in SqCLC samples." (PMID 19961602, 2009). "Expression of RARα, RARβ, RARγ, RXRα and RXRβ was found in most cell types in gastric mucosa tissues from normal individuals as well as in distal normal tissues from cancer patients." (PMID 10389997, 1999). "RXRB is a member of the retinoid X receptor families involved in cancer development and stemness." (PMID 38711144, 2024). "This trend was also observed in other cancer types and for the RXRβ isoform." (PMID 34638488, 2021). "The RAB39A‒RXRB axis drives cancer stemness and tumorigenesis; consequently, the downregulation of this pathway leads to poor sphere formation and xenotransplantable function in several types of malignancies, such as sarcomas, adrenal, lymphoid, and testicular tumors." (PMID 33525614, 2021). "It is why inhibiting RAB39A or RXRB can critically affect cancer stemness." (PMID 29515775, 2018). "Furthermore, our group recently found that retinol dehydrogenase 10 (RHD10), enzymes related to vitamin A metabolism and gluconeogenesis, can reflect cancer stemness through precise analyses of the RAB39A (a member of the RAS oncogene family)‒RXRB (retinoid X receptor beta) axis." (PMID 33525614, 2021). "The expression of RARβ as well as RXRβ was reported to be downregulated in NSCLC, which enabled the cancer cell to evade apoptosis." (PMID 32293355, 2020). "Our data clearly demonstrated that RAB39A and its downstream molecular effector RXRB fostered cancer stemness and tumorigenesis, and that RAB39A-RXRB axis is a potential target for cancer therapies." (PMID 29515775, 2018). "The mutual heterodimers of RXRB and vitamin D receptor (VDR) promoted the development of cancer, and activated the Ras-Raf-MAPK-ERK signaling pathway to involve in the dominating VDR pathway for various gene expressions regulation (Deeb, Trump & Johnson, 2007)." (PMID 39465162, 2024). "Rab39a and its downstream effector Retinoid X Receptor Beta (RXRB), a member of the retinoid X receptor, are instead involved in cancer stemness regulation as silencing of Rab39a and inhibition of RXRB impairs tumorigenesis and cancer stemness." (PMID 31426400, 2019).
cancer (continued). "As RAB39A is involved in lysosome maturation and, according to our presented data, also in cancer stemness, we investigated whether hypoxia might modulate the expressions of RAB39A and RXRB, and mediate CSC survival under hypoxic conditions." (PMID 29515775, 2018). "RXRB is a member of the retinoid X receptor (RXR) families mediating the effects of retinoic acid, and the mutual heterodimers with vitamin D receptor (VDR) are involved in cancer developments." (PMID 29515775, 2018). "Interestingly, RXRB, previously highlighted in cancer cell lines, did not present with a statistically significant fold regulation in any cancer type." (PMID 39766077, 2024). "Together, the clinical sample data strengthen our hypothesis that RXRB is a downstream effector of RAB39A, and that RAB39A-targeting treatments will selectively affect cancer cells and be unlikely to cause undue side effects in normal tissues." (PMID 29515775, 2018). "RXRB was expressed in different cancers, irrespective of the tumor histotype." (PMID 29515775, 2018).
tumor (12 papers, 2014 to 2026). "The results of this study also demonstrate that expression changes in the genes of the inferred RXRB-causal network are significantly associated with increased risks of tumor relapse, distant metastases and poor survival outcomes." (PMID 24322297, 2014). "Our findings suggest that the detailed functions of the RXRB-causal network in tumor metastasis should be investigated further." (PMID 24322297, 2014). "One such study determined the expression of RARs in normal and malignant tissues from 76 patients with NSCLC and showed that tumor cells have overexpressed RXRα and RARα and reduced RXRβ, RARβ, and RARγ." (PMID 35631448, 2022). "Another study reported the overexpression of RXRα in cancer cells, and RXRβ expression, on the other hand, reduced in 18% of tumor samples." (PMID 35631448, 2022). "The expression of RARβ and RXRβ has been reported to be downregulated in NSCLC enabling their ability to evade apoptosis and have been associated with tumour development and prognosis." (PMID 33550205, 2021). "RXRB overexpression in the RXRB_shRAB cells restored tumor growth potential to the similar or more level as the RXRB_shCont cells." (PMID 29515775, 2018). "In our tumor samples, we determined large amounts of the RARα, RARβ, RXRα and RXRβ transcripts." (PMID 39323992, 2024). "Consequently, the downstream effectors of RXRB also exhibit detrimental effects on tumor relapse and poor survival in OSCC." (PMID 24322297, 2014). "The tumor cells from the endometrium, esophagus, thyroid, and kidneys show dominant expressions of receptors like RXRA (Retinoid X Receptor Alpha), RXRB, PPARG, and ADORA1 (Adenosine A1 Receptor), underscoring their diverse physiological roles." (PMID 39766077, 2024). "The analysis revealed that the expression levels of RXRB and CDK2 were higher in lower pathological stages of the tumor." (PMID 37509183, 2023). "Nevertheless, unexpectedly, enhanced PXR/RXRβ expression correlated with smaller tumor size and the absence of lymph node metastases and longer survival." (PMID 32344895, 2020). "Furthermore a higher PXR expression correlates with a higher histological grade of pancreatic adenocarcinoma, while enhanced PXR/RXRβ expression correlates with a smaller tumor size, the absence of lymph node metastases, and longer survival." (PMID 32344895, 2020). "Interestingly, RXRB expression levels were significantly correlated with RAB39A expression levels only in tumor tissues (r = 0.205, n = 325, p = 0.0002) and not in normal tissues (r = 0.202, n = 69, p = 0.0968)." (PMID 29515775, 2018). "In the clinical sample analysis, RXRB levels were not correlated with RAB39A expression levels in normal tissues, but a significant correlation was present in tumor tissues." (PMID 29515775, 2018).
RXRB also shares sentences with these, for which no sentence is quoted: allergic rhinitis (1 paper); Allergy (1); asthma (1); Cohen syndrome (1); colorectal cancer (1); diabetic retinopathy (1); fragile X syndrome (1); glioblastoma (1); glioma (1); invasive breast carcinoma (1); Kaposi's sarcoma (1); lymph node metastasis (1); lymphoma (1); osteosarcoma (1); pheochromocytoma (1); prostate carcinoma (1); psoriasis (1); sarcoma (1); stomach tumors (1); testicular germ cell tumor (1); tuberculosis (1); xeroderma pigmentosum (1).